RIMKLB (ribosomal modification protein rimK like family member B)
Description:
Catalyzes the synthesis of beta-citryl-L-glutamate and N-acetyl-L-aspartyl-L-glutamate. Beta-citryl-L-glutamate is synthesized more efficiently than N-acetyl-L-aspartyl-L-glutamate.
Synonyms: NAAGS; FAM80B; KIAA1238; NAAGS-I
Tractability: PROTAC: ubiquitination databases record sites on it.
Gene: Protein-coding gene on chromosome 12 (8,681,483 to 8,783,095, forward strand). Ensembl gene ENSG00000166532.
Subcellular location: Cytoplasm
Subcellular location (Human Protein Atlas): Centriolar satellite; Nucleoplasm
Pathways (Reactome):
Metabolism: Glutamate and glutamine metabolism
Gene Ontology:
Molecular function: citrate-L-glutamate ligase activity; N-acetyl-L-aspartate-L-glutamate ligase activity; ATP binding; metal ion binding
Biological process: L-amino acid metabolic process; L-glutamate catabolic process
Cellular component: cytoplasm; cytosol
Genetic constraint (gnomAD): Loss-of-function variants: 5 observed, 23.62 expected, observed/expected ratio (o/e) 0.21, 90% interval 0.11 to 0.44. The upper end of that interval is the gene's LOEUF score, 0.44, which puts it in group 1 of 6, group 1 being the genes least tolerant of losing a copy. Missense variants: 260 observed, 444.86 expected, observed/expected ratio (o/e) 0.58, 90% interval 0.53 to 0.65. Synonymous variants: 147 observed, 166.71 expected, observed/expected ratio (o/e) 0.88, 90% interval 0.77 to 1.01.
Homologues: Orthologues: chimpanzee RIMKLB (100% identical), macaque RIMKLB (100% identical), dog RIMKLB (99% identical), rabbit RIMKLB (99% identical), guinea pig RIMKLB (99% identical), rat Rimklb (97% identical), mouse Rimklb (97% identical), rat Rimklbl1 (97% identical), tropical clawed frog rimklb (87% identical), pig RIMKLB (74% identical). Paralogues in human: RIMKLA (68% identical).
Diseases named in the same sentence as RIMKLB in open-access papers:
RIMKLB is named in the same sentence as 15 diseases in open-access papers, as found by Europe PMC text mining. Sharing a sentence is not in itself a finding about the gene and the disease. The quoted sentences say what the papers report.
colon cancer (1 paper, 2022). "The GEPIA database was used to analyze the expression of RIMKLB TPM in colon cancer and rectum cancer." (PMID 35444692, 2022). "Moreover, we also performed subgroup analysis via tumor site to determine whether the role of RIMKLB in colon cancer is different from that in rectum cancer." (PMID 35444692, 2022). "High expression of RIMKLB in rectal cancer indicated poor OS and DFS, while there was no significant statistical correlation in the case of colon cancer." (PMID 35444692, 2022).
colorectal cancer (1 paper, 2022). A primary or metastatic malignant neoplasm that affects the colon or rectum. "The Oncoprint and Mutation tab shows that the RIMKLB gene is altered in 2.5% of the total patients in TCGA colorectal cancer dataset along with the heatmap for the associated genes." (PMID 35444692, 2022). "RIMKLB is associated with local immunity in colorectal cancer, and its abnormal expression may lead to the occurrence and development of CRC." (PMID 35444692, 2022). "Collectively all these results reveal that the RIMKLB gene has a positive association and correlation with AKT3, MPDZ, PKD2, and MAP1B to upregulate the gene expression to induce the development of colorectal cancer." (PMID 35444692, 2022). "Therefore, we used TIMER database to investigate the relationship between RIMKLB expression and immunotherapeutic targets in colorectal cancer." (PMID 35444692, 2022). "However, the relationships among RIMKLB expression, survival outcomes, and tumor-infiltrating immune cells (TIICs) in colorectal cancer (CRC) are still unknown." (PMID 35444692, 2022).
heart failure (1 paper, 2024). Inability of the heart to pump blood at an adequate rate to meet tissue metabolic requirements. "Recent studies have identified the role of RIMKLB in maintaining the balance of zinc and copper ions within the epicardial adipose tissue during heart failure." (PMID 39553847, 2024).
mucinous adenocarcinoma (1 paper, 2022). An invasive adenocarcinoma composed of malignant glandular cells which contain intracytoplasmic mucin. "The results revealed that the mRNA expression of RIMKLB was significantly increased in the mucinous adenocarcinoma (p < 0.001), rectum (p < 0.001), lymph node stage (N0) (p = 0.0485), advanced stages (III/IV) (p < 0.001), and with tumor (p < 0.001)." (PMID 35444692, 2022).
nasopharyngeal carcinoma (1 paper, 2018). A carcinoma arising from the nasopharyngeal epithelium. "RIMKLB up-regulation is associated with radio-resistance in nasopharyngeal carcinomas." (PMID 29915691, 2018).
rectum cancer (1 paper, 2022). "In our study, we found that in colon and rectal cancer, the expression level of RIMKLB was significantly correlated with most immune marker groups of various immune cells and different T cells." (PMID 35444692, 2022).
triple-negative breast carcinoma (1 paper, 2024). An invasive breast carcinoma which is negative for expression of estrogen receptor (ER), progesterone receptor (PR), and human epidermal growth factor receptor 2 (HER2). "Notably, the TRs of several genes, including SYNGR1, GTF2IRD2, and FAM120C, exhibited increased levels in the tumor samples of triple-negative breast cancer patients, whereas genes such as TVP23C, ICAM3, and RIMKLB displayed decreased TRs in triple-negative breast cancer tumor samples." (PMID 39349823, 2024).
tumor (3 papers, 2022 to 2024). "In COAD and READ, the expression of RIMKLB maintained a high degree of consistency with tumor immune cell infiltration and the expression of immune examination, except for B cell infiltration and PD1 expression." (PMID 35444692, 2022). "Tumor growth was significantly decreased with the knockdown of RIMKLB and was partly rescued with NAAG supplementation." (PMID 35105939, 2022). "After we supplied 50 μM NAAG into the medium, the tumor inhibitory effect of RIMKLB depletion was partially rescued." (PMID 35105939, 2022). "TIMER analysis indicated that RIMKLB transcription was closely related with several TIICs, including CD4+ and CD8+ T cells, B cells, tumor-associated macrophages (TAMs), monocytes, neutrophils, natural killer cells, dendritic cells, and subsets of T cells." (PMID 35444692, 2022). "Some studies have found that RIMKLB can affect reproductive function of mammals, and in tumor research, RIMKLB may coordinate with DDIT4 function to mediate mTOR inhibition and growth inhibition of tumor cells." (PMID 35444692, 2022). "Therefore, based on a list of public databases, our study aimed to determine the correlation between RIMKLB expression and tumor-infiltrating immune cells (TIICs) in CRC." (PMID 35444692, 2022). "Moreover, multiple databases confirmed that a high expression of RIMKLB was associated with worse OS and DFS, indicating that this gene may play an important role in tumor development." (PMID 35444692, 2022). "The RIMKLB expression was significantly decreased in CRC compared to normal tissues, and correlated with histology, stage, lymphatic metastasis, and tumor status (p < 0.05)." (PMID 35444692, 2022). "To determine the difference expression of RIMKLB between tumor and normal tissue, we used the UALCAN database to analyze the expression levels of RIMKLB in normal tissues of different tumors and multiple cancer types." (PMID 35444692, 2022).
cancer (1 paper, 2022). A tumor composed of atypical neoplastic, often pleomorphic cells that invade other tissues. "We also verified the prognostic value of RIMKLB expression in CRC cancers using the Prognoscan website, whose data were from GEO database." (PMID 35444692, 2022).
RIMKLB also shares sentences with these, for which no sentence is quoted: Azoospermia (1 paper); glioblastoma (1); paraganglioma (1); pheochromocytoma (1); thymoma (1); uterine corpus endometrial carcinoma (1).